NCS1 (neuronal calcium sensor 1)
Description:
Neuronal calcium sensor, regulator of G protein-coupled receptor phosphorylation in a calcium dependent manner. Directly regulates GRK1 (RHOK), but not GRK2 to GRK5. Can substitute for calmodulin (By similarity). Stimulates PI4KB kinase activity (By similarity). Involved in long-term synaptic plasticity through its interaction with PICK1 (By similarity). May also play a role in neuron differentiation through inhibition of the activity of N-type voltage-gated calcium channel (By similarity).
Synonyms: NCS-1; FLUP; FREQ
Tractability: Small molecule: a structure with a bound ligand is known; it has a binding pocket of medium quality. Antibody: UniProt places it where antibodies can reach, with high confidence; its Gene Ontology location is reachable by antibodies, with high confidence; the Human Protein Atlas places it where antibodies can reach. PROTAC: ubiquitination databases record sites on it; its protein half-life has been measured; a small molecule that binds it is known.
Gene: Protein-coding gene on chromosome 9 (130,172,347 to 130,237,303, forward strand). Ensembl gene ENSG00000107130.
Subcellular location: Golgi apparatus; Postsynaptic density; Cytoplasm, perinuclear region; Cytoplasm; Cell membrane; Membrane
Subcellular location (Human Protein Atlas): Plasma membrane; Cytosol; Vesicles
Gene Ontology:
Molecular function: protein binding; calcium ion binding; calcium sensitive guanylate cyclase activator activity; voltage-gated calcium channel activity
Biological process: regulation of neuron projection development; regulation of signal transduction; calcium ion transmembrane transport
Cellular component: cytoplasm; cytosol; Golgi apparatus; plasma membrane; membrane; axon; dendrite; perinuclear region of cytoplasm; postsynaptic density
Genetic constraint (gnomAD): Loss-of-function variants: 5 observed, 27.37 expected, observed/expected ratio (o/e) 0.18, 90% interval 0.094 to 0.38. The upper end of that interval is the gene's LOEUF score, 0.38, which puts it in group 1 of 6, group 1 being the genes least tolerant of losing a copy. Missense variants: 130 observed, 234.81 expected, observed/expected ratio (o/e) 0.55, 90% interval 0.48 to 0.64. Synonymous variants: 86 observed, 95.51 expected, observed/expected ratio (o/e) 0.9, 90% interval 0.75 to 1.08.
Homologues: Orthologues: mouse Ncs1 (100% identical), pig NCS1 (100% identical), tropical clawed frog ncs1 (99% identical), zebrafish ncs1b (98% identical), zebrafish ncs1a (96% identical), Caenorhabditis elegans ncs-2 (43% identical), Drosophila melanogaster CG7646 (43% identical), Drosophila melanogaster CG5890 (36% identical), Caenorhabditis elegans ncs-7 (33% identical). Paralogues in human: HPCAL1 (59% identical), NCALD (58% identical), HPCA (58% identical), VSNL1 (57% identical), HPCAL4 (55% identical), KCNIP2 (45% identical), KCNIP1 (45% identical), KCNIP4 (45% identical), KCNIP3 (44% identical), RCVRN (44% identical), GUCA1B (38% identical), GUCA1A (36% identical), and 2 more.
Diseases named in the same sentence as NCS1 in open-access papers:
NCS1 is named in the same sentence as 76 diseases in open-access papers, as found by Europe PMC text mining. Sharing a sentence is not in itself a finding about the gene and the disease. The quoted sentences say what the papers report.
schizophrenia (15 papers, 2010 to 2025). A major psychotic disorder characterized by abnormalities in the perception or expression of reality. "Alterations in NCS-1 function have been implicated in a number of human diseases including schizophrenia, bipolar disease and chemotherapy-induced peripheral neuropathy." (PMID 27575489, 2016). "Modifications to the expression or mutation of NCS-1 are also associated with schizophrenia, bipolar disease, autism, and chemotherapy-induced peripheral neuropathy." (PMID 27575489, 2016). "Accordingly, numerous studies provided genetic and experimental evidence for the involvement of NCS‐1 in several neurological disorders such as bipolar disorder, schizophrenia and autism (review in Ref." (PMID 32530132, 2021). "Peripheral biomarker and post-mortem brains studies have shown alterations of neuronal calcium sensor 1 (Ncs-1) expression in people with bipolar disorder or schizophrenia." (PMID 32165725, 2020). "Although evidence suggests that Ncs-1 is affected in schizophrenia and bipolar disorder, the effect of psychiatric medications on Ncs-1 remains unexplored." (PMID 32165725, 2020). "A connection between defective NCS-1 and neurodegenerative disorders like schizophrenia, autism and bipolar disorder has also been suggested." (PMID 30618617, 2018). "NCS-1 is upregulated in patients with schizophrenia or bipolar disorder as well as in the substantia nigra from Parkinson’s disease patients, and a mutation in NCS-1 was found in a case of autistic spectrum disorder." (PMID 29523177, 2018). "Samples of the prefrontal cortex of patients with schizophrenia and bipolar disorder exhibit increased expression of NCS-1." (PMID 28122057, 2017). "Therefore, our findings reinforce the suggestion that both downregulation of DARPP-32 and upregulation of NCS-1 reported to occur in the PFC of schizophrenia patients, might be associated with the psychopathology of the disorder but not with antipsychotic treatment." (PMID 20565907, 2010). "In previous studies linking NCS-1 to disease states, it has been found that expression of NCS-1 is elevated in the prefrontal cortices of patients with schizophrenia and bipolar disorder, and is up-regulated in injured neurones and in epilepsy." (PMID 20479890, 2010). "The D1R‐interacting protein calcyon and the D2R‐interacting protein neuronal calcium sensor‐1 (NCS‐1) were elevated in the prefrontal cortex of schizophrenia patients, suggesting that DRIPs might be related to schizophrenia." (PMID 37248637, 2023). "Notably, NCS1 levels have been assessed as a biomarker in peripheral blood in bipolar disorder and schizophrenia, supporting testing NCS1 as a biomarker for CIPN and CRCI." (PMID 36206298, 2022). "Neuronal calcium sensor-1 (NCS-1; also called frequenin) is a 190-residue protein, belonging to the NCS subfamily of EF-hands that potentiates neurotransmitter release and it has been linked to several human disorders including autism and schizophrenia." (PMID 32936312, 2021). "It was observed that in comparison to healthy individuals, patients suffering from schizophrenia had upregulated levels of NCS-1 in the prefrontal cortex, which may explain their reduced prefrontal cortex activity." (PMID 30618617, 2018). "Indeed, the expression pattern of Ncs-1 is altered in schizophrenia and bipolar disorder patients." (PMID 32165725, 2020). "Although the underlying mechanism of changes in NCS-1 expression in schizophrenia and bipolar disorder is not known, it might be associated with the altered Ca2+ signaling reported in these disorders." (PMID 21647420, 2011). "Moreover, in addition to the relationship between the PI4KB activator NCS‐1 and schizophrenia, genetic and functional linkages were also observed between the PI4KB inhibitor CALN‐1 and schizophrenia." (PMID 32530132, 2021).
schizophrenia (continued). "In postmortem studies, increased neuronal calcium sensor protein-1 (NCS-1) expression was present in schizophrenia and bipolar disorder patients, but not in major depression patients." (PMID 25368599, 2014).
bipolar disorder (11 papers, 2010 to 2025). A disorder of the brain that causes unusual shifts in mood, energy, activity levels and the ability to carry out day-to-day tasks. "NCS1 upregulation has been reported in psychiatric diseases including bipolar disorder and downregulation has been observed in neuronal tissues of multiple neurodegenerative diseases such as Parkinson disease." (PMID 36206298, 2022). "Pathologically, NCS-1/InsP3R1 interaction is believed to be involved in bipolar disorder because lithium, a medical drug for bipolar disorder, inhibited the NCS-1-induced enhancement of InsP3R function." (PMID 30886571, 2019). "Postmortem studies showed increased expression of neuronal calcium sensor protein 1 (NCS‐1) in the brains of some bipolar disorder patients, and reduced or aberrant gamma band activity is present in the same disorder." (PMID 28408639, 2017). "Human postmortem studies reported increased expression of neuronal calcium sensor protein 1 (NCS‐1) in the brains of some bipolar disorder patients, and reduced or aberrant gamma band activity is present in the same disorder." (PMID 27033453, 2016). "Lithium (Li+) has been shown to effectively treat the mood disturbances in bipolar disorder patients and was proposed to act by inhibiting the interaction between NCS‐1 and inositol 1,4,5‐triphosphate receptor protein (InsP3R)." (PMID 27033453, 2016). "NCS-1 is upregulated in the prefrontal cortex of patients with schizophrenia and bipolar disorder." (PMID 30886571, 2019). "We investigated the effect on Ncs-1 expression of valproic acid (VPA), a mood stabilizer used for the management of bipolar disorder." (PMID 32165725, 2020).
Parkinson disease (11 papers, 2009 to 2025). A progressive degenerative disorder of the central nervous system characterized by loss of dopamine producing neurons in the substantia nigra and the presence of Lewy bodies in the substantia nigra and locus coeruleus. "Consistent with this, knockout of NCS-1 resulted in more severe dopaminergic neuronal loss in our Parkinson’s disease model." (PMID 31704946, 2019). "Abnormalities in the expression and function of NCS-1, as well as hereditary mutations in its gene, are associated with neurodegenerative and neuropsychiatric diseases, including schizophrenia, autism, Alzheimer’s disease, and Parkinson’s disease." (PMID 34830487, 2021). "Importantly, NCS-1 expression is reduced in iPSC-derived dopaminergic neurons from familial Parkinson’s disease patients heterozygous for the N370S mutation in the GBA1 gene." (PMID 31704946, 2019). "Other movement disorders, such as Parkinson’s disease have shown the influence of NCS-1 in neuronal activity of dopaminergic neurons." (PMID 35401706, 2022). "We therefore applied the same chronic MPTP Parkinson’s disease model to NCS-1 knockout mice and wildtype controls." (PMID 31704946, 2019). "In contrast, the lower NCS-1 levels detected in iPSC-derived dopaminergic neurons from GBA-1 Parkinson’s disease patients, offers an explanation for their accelerated degeneration." (PMID 31704946, 2019). "In our final analysis, we compared NCS-1 and Cav2.3 protein levels in a human model of Parkinson’s disease." (PMID 31704946, 2019). "Changes in NCS-1 expression will alter the relation with its target proteins and were described in a variety of diseases, including schizophrenia and Parkinson’s disease, both characterized by dysfunctional dopaminergic signaling." (PMID 31827421, 2019). "NCS-1 thus emerges as protective factor during SN dopaminergic degeneration, of likely relevance to Parkinson’s disease." (PMID 31704946, 2019). "We also made an unexpected observation that NCS-1 interacts with several mitochondrial proteins, including Pink1, a gene that contributes to familial Parkinson's disease." (PMID 19320994, 2009). "Here the authors find that the R-type channel Cav2.3 in substantia nigra dopaminergic neurons may contribute to neurodegeneration in a model of Parkinson’s disease, in contrast to the neuroprotective action of the neuronal Ca2+ sensor NCS-1." (PMID 31704946, 2019). "Here, we combine single-cell molecular techniques, brain slice patch-clamp recordings and Ca2+ imaging with pharmacological and genetic tools to analyze the role of voltage-gated Ca2+ channels and NCS-1 for dopaminergic neuronal viability in Parkinson’s disease." (PMID 31704946, 2019). "We hypothesize that functional expression of protective NCS-1 in SN dopaminergic neurons might get upregulated in response to Parkinson’s disease stressors." (PMID 31704946, 2019). "Collectively, our data strongly suggest opposing roles for Cav2.3 and NCS-1 in Parkinson’s disease." (PMID 31704946, 2019). "It will be important to determine whether NCS-1 serves to regulate Pink1 function, either within mitochondria or other cellular compartments, and whether the NCS-1/Pink1 interaction contributes to the etiology of Parkinson's disease." (PMID 19320994, 2009). "Thus, Cav2.3 and NCS-1 may constitute potential therapeutic targets for combatting Ca2+-dependent neurodegeneration in Parkinson’s disease." (PMID 31704946, 2019). "However, to date, the TRPA1 channel has not been linked with NCS-1, although some of the most essential functions of TRPA1 appear to require a close relationship with this Ca2+ sensor, such as memory, neuronal survival, cell death, Parkinson’s disease, CIPN, and cancer." (PMID 38564162, 2024).
breast carcinoma (9 papers, 2018 to 2025). "Our identification that NCS‐1 is most associated with the basal breast cancer further defines the potential subtype‐specific contribution of NCS‐1 to breast cancer progression." (PMID 31647602, 2020). "Herein, we report for the first time an increased expression of NCS‐1 in breast cancers of the basal molecular subtype, a subtype associated with poor prognosis." (PMID 31647602, 2020). "This work defines a clear association between NCS‐1 and the basal breast cancer molecular subtype, a subtype with poor prognosis." (PMID 31647602, 2020). "Given that NCS‐1 was recently reported to be associated with increased breast tumor aggression and poor prognosis, we explored if NCS‐1 is associated with any of the breast cancer intrinsic molecular subtypes using TCGA breast cancer database." (PMID 31647602, 2020). "Here, we determine if NCS-1 expression is associated with pathological complete response (pCR) to taxane-based neoadjuvant chemotherapy in 105 pre-treatment breast cancer biopsies." (PMID 29560416, 2018). "In addition to the effects on neuronal function, high expression of NCS1 in tumor tissues is associated with poor outcomes in both breast cancer and liver cancer patients." (PMID 36206298, 2022). "However, the association between NCS‐1 and breast cancer molecular subtypes and the effects of NCS‐1 silencing on calcium (Ca2+) signaling in breast cancer cells remain unexplored." (PMID 31647602, 2020). "Further exploration into the relevance of NCS1 in breast cancer progression showed that knockout of NCS1 (NCS1 KO) caused decreased cell survival and motility, increased baseline intracellular Ca2+ levels, and decreased inositol 1,4,5‐trisphosphate‐mediated Ca2+ responses." (PMID 32239615, 2020). "Alternatively, the positive association between ORAI1 and NCS‐1 may be due to their association with breast cancers of the basal molecular subtype." (PMID 31647602, 2020). "The association of NCS‐1 expression with breast cancer molecular subtypes also remains unexplored." (PMID 31647602, 2020). "Despite reports of NCS‐1 being associated with therapeutic response to paclitaxel, it remains unknown if this is associated with changes in Ca2+ signaling in breast cancer cells." (PMID 31647602, 2020). "Another interesting result was obtained in the same type of breast cancer cells used in this study, where NCS-1 elicited enhanced cell survival, motility, and metastatic spread through the PI3K pathway." (PMID 38564162, 2024). "This correlates with in vivo studies, where the expression of NCS-1 is higher in breast cancer cells, and the level of increase is significantly correlated with shorter survival rates in breast cancer patients." (PMID 38564162, 2024). "In clinical trials, expression of NCS-1 was also a predictive biomarker for the response to taxane-based neoadjuvant chemotherapy in breast cancer, and doxorubicin-induced breast cancer cell death." (PMID 38564162, 2024). "Conversely, NCS‐1 expression is negatively correlated to FOXA1, ESR1, and PGR, which are more commonly associated with the breast cancer luminal subtype." (PMID 31647602, 2020). "Silencing of NCS‐1 suppresses basal calcium (Ca2+) influx and increases cell death induced by doxorubicin treatment in basal breast cancer cells." (PMID 31647602, 2020). "Because the InsP3R is known to regulate cancer progression, we aimed to determine how NCS1 affects cellular Ca2+ homeostasis and signaling in breast cancer cells." (PMID 32239615, 2020). "We also demonstrate that siRNA‐mediated silencing of NCS‐1 attenuated unstimulated basal Ca2+ influx in basal breast cancer cells." (PMID 31647602, 2020). "NCS‐1 silencing also enhanced cell death induced by doxorubicin treatment in MDA‐MB‐231 breast cancer cells." (PMID 31647602, 2020). "Neuronal calcium sensor‐1 (NCS‐1) is a positive modulator of IP3 receptors and was recently associated with poorer survival in breast cancers." (PMID 31647602, 2020).